NIPAL2 (NIPA like domain containing 2)
Synonyms: NPAL2; FLJ13955; SLC57A4
Tractability: Antibody: UniProt predicts a signal peptide or a membrane-spanning region.
Gene: Protein-coding gene on chromosome 8 (98,189,826 to 98,294,393, reverse strand). Ensembl gene ENSG00000104361.
Subcellular location: Membrane
Pathways (Reactome):
Transport of small molecules: Miscellaneous transport and binding events
Gene Ontology:
Molecular function: magnesium ion transmembrane transporter activity
Biological process: magnesium ion transport; magnesium ion transmembrane transport
Cellular component: membrane
Genetic constraint (gnomAD): Loss-of-function variants: 17 observed, 24.28 expected, observed/expected ratio (o/e) 0.7, 90% interval 0.48 to 1.05. The upper end of that interval is the gene's LOEUF score, 1.05, which puts it in group 4 of 6, group 1 being the genes least tolerant of losing a copy. Missense variants: 302 observed, 293.92 expected, observed/expected ratio (o/e) 1.03, 90% interval 0.93 to 1.13. Synonymous variants: 130 observed, 115.85 expected, observed/expected ratio (o/e) 1.12, 90% interval 0.97 to 1.3.
Homologues: Orthologues: chimpanzee NIPAL2 (98% identical), macaque NIPAL2 (96% identical), pig NIPAL2 (90% identical), guinea pig NIPAL2 (89% identical), dog NIPAL2 (86% identical), mouse Nipal2 (85% identical), rat Nipal2 (85% identical), tropical clawed frog nipal2 (54% identical). Paralogues in human: NIPAL3 (44% identical), NIPAL1 (25% identical), NIPAL4 (25% identical), NIPA2 (25% identical), NIPA1 (16% identical).
Diseases named in the same sentence as NIPAL2 in open-access papers:
NIPAL2 is named in the same sentence as 1 disease in open-access papers, as found by Europe PMC text mining. Sharing a sentence is not in itself a finding about the gene and the disease.
NIPAL2 shares sentences with these, for which no sentence is quoted: tumor (1 paper).